INS (insulin)
Diseases named in the same sentence as INS in open-access papers (continued):
Sharing a sentence is not in itself a finding about the gene and the disease.
diabetes (continued). "The insulin output adequately corrects diabetic hyperglycemia and restores many diabetes-associated parameters of anomalous metabolism to normal, including the normal rate of weight gain in insulin gene-treated diabetic animals." (PMID 23826312, 2013). "Ovarian cancer is the deadliest gynecological malignancy affecting American women, and obesity and diabetes are associated with a worse prognosis due in part to the effects of elevated levels of insulin and IGF on cancer cells." (PMID 23388061, 2013). "This glucose moiety selectively destroys the insulin-producing β-cells of the pancreas leading to rapid insulin-deficiency and diabetes." (PMID 23730303, 2013). "Diabetes mellitus is a clinical syndrome characterized by inappropriate hyperglycemia caused by a relative or absolute deficiency of insulin or by a resistance to the action of insulin at the cellular level." (PMID 23834750, 2013). "While relative deficiency of insulin and hyperglycemia are well studied in diabetes, the harmful effects of insulin excess are poorly recognized except where they result in hypoglycemia." (PMID 24204385, 2013). "The results of the present study are in agreement with previous prospective studies, showing that people with diabetes treated with oral hypoglycemic drugs or insulin have a higher risk of death from cardiovascular disease than those without medication." (PMID 23738538, 2013). "In Japan, approximately half of all patients with diabetes have a genetic predisposition to the disease, and insulin secretion is often impaired in lean patients with diabetes mellitus." (PMID 23339473, 2013). "The mechanisms by which HIMP1 overexpression at lower levels enhances basal insulin production and β-cell survival while at toxic higher levels causing β-cell failure and diabetes deserve further study." (PMID 22470529, 2012). "Although the detailed pathogenic mechanisms of diabetes are still elusive, impaired insulin signaling and dys-regulated gene expression have been investigated in this disease." (PMID 22384078, 2012). "Type 2 diabetes mellitus (T2DM) is a chronic disease caused by deficient insulin secretion or ineffective insulin activity, which negatively affects carbohydrate metabolism." (PMID 22548048, 2012). "Diabetes is a syndrome characterized by chronic hyperglycaemia with disturbances in protein, lipid and carbohydrate metabolism owing to a deficiency in insulin production, action or both." (PMID 23024779, 2012). "Longer duration of diabetes is known to be associated with poor glycemic control, possibly due to progressive impairment of insulin secretion because of beta cell failure, compounding the adverse effects of insulin resistance." (PMID 23119180, 2012). "Further to β-cell dysfunction and insulin secretory deficit in diabetes, defects in insulin receptor (InsR) expression or function can cause insulin resistance and diabetes mellitus." (PMID 23213296, 2012). "UKPD study showed that metformin decreased the risk of diabetes-related end points and was associated with less weight gain and lesser hypoglycemic events compared with sulfonylureas and insulin." (PMID 23882374, 2012). "Diabetes mellitus is a chronic metabolic disorder caused by defects in insulin secretion, insulin action, or both." (PMID 22905094, 2012). "The recent discovery of hepcidin, the key iron regulatory hormone, has changed our view of iron metabolism, which in turn is long known to be linked with insulin resistant states, including type 2 diabetes mellitus and the Metabolic Syndrome (MetS)." (PMID 23144745, 2012). "Diabetes is a chronic metabolic disease which is characterized by absolute or relative deficiencies in insulin secretion and/or insulin action." (PMID 22007193, 2012). "Most discovered diabetes-risk variants have a predominant effect on insulin secretion, and there are only few that markedly influence body adiposity and insulin sensitivity." (PMID 22768041, 2012).
diabetes (continued). "The mechanisms by which modulation of postprandial glycaemia can interfere with insulin sensitivity and secretion and thus the risk of diabetes involve the concept of glucolipotoxicity." (PMID 22780564, 2012). "Consistent with epidemiological investigations showing that diabetes is an important risk factor for sporadic AD, a growing body of evidence indicates defective insulin signaling in AD brains." (PMID 22403710, 2012). "Among the categorical variables, both impaired glucose regulation and insulin intake during pregnancy were confirmed being associated with diabetes development (HRIGR = 14.64 (5.16–41.48), P<0.0001, HRINS_PREGN = 11.07 (1.47–83.20), P<0.02)." (PMID 23185618, 2012). "The use of insulin is important to effectively control the disease process in patients with diabetes mellitus and insulin adherence has been especially proven to be associated with good long term metabolic control." (PMID 23199230, 2012). "IR is a state of impaired metabolic response to insulin as characterized by the American Diabetes Association (ADA)." (PMID 22276997, 2012). "The pathophysiology of diabetes mellitus is mainly due to decreased insulin secretion associated with pancreatic fibrosis." (PMID 22284844, 2012). "Diabetes mellitus is a chronic metabolic disorder characterized by elevated blood glucose levels (hyperglycemia) caused by decreased secretion of insulin, impaired insulin signaling, or both." (PMID 23247284, 2012). "Type 1 diabetes mellitus is one of the metabolic diseases that cause insulin-producing pancreatic ß cells be destroyed by immune system self-reactive T cells." (PMID 23843817, 2012). "Our results should prompt further investigations to decipher insulin signaling pathways in the brain and a detailed analysis of the transcriptional regulation of diabetes-associated genes having been identified in this study." (PMID 22369239, 2012). "MODY patients are mainly characterized by a severe impairment of insulin secretion, and MODY gene products, including HNF4α, are monogenic causes of an insulin secretion defect resulting in diabetes." (PMID 22952853, 2012). "Some pathological conditions, including diabetes, which are associated with membrane defects, can be improved with insulin therapy." (PMID 22007193, 2012). "It has been proved that insulin-degrading enzyme (IDE), which can reduce the levels of brain A β and insulin, is associated with AD and type 2 diabetes mellitus." (PMID 22792090, 2012). "Last, total WBC count is associated with insulin sensitivity such that an increase in total WBC count is indicative of an increased risk of future type 2 diabetes mellitus." (PMID 22363616, 2012). "The effects of ablation of glucagon actions on the development of insulin-deficient diabetes have been studied in glucagon receptor knockout mice (Gcgr−/−)." (PMID 23316165, 2012). "We confirmed and extended the previous findings by determining the mechanisms by which STZ-induced insulin-deficient diabetes aggravates β-amyloidosis in 5XFAD transgenic mice." (PMID 22403710, 2012). "Diabetes medications including insulin and sulphonylureas are among the most common causes of hypoglycemia in diabetic subjects." (PMID 23497433, 2012). "In a recent study, fewer women with GDM, who were receiving a low GI diet, needed insulin during pregnancy, when compared to the American Diabetes Association diet." (PMID 23251152, 2012). "Since the discovery of insulin in 1921, the external regulation of diabetes by engineering means has became a hallmark of this optimization." (PMID 24278682, 2012). "Here, we review how aging predisposes to diabetes and impaired glucose tolerance through effects on insulin secretion and insulin action." (PMID 22675349, 2012). "It has been suggested that relieving the β-cells in the pre-diabetes state by inhibition of insulin secretion, would be a sensible way to protect the β-cells and thus lower the risk of development of diabetes." (PMID 23110768, 2012).
diabetes (continued). "NeuroD1-deficiency in mice causes severe diabetes and perinatal lethality because NeuroD1 is required for insulin gene expression." (PMID 22988465, 2012). "Diabetes mellitus Type 2 (T2D) is usually caused by peripheral insulin resistance together with inadequate insulin secretion by the pancreatic beta cells." (PMID 22649445, 2012). "From the first studies recognizing the abundance of insulin and IR in brain to its potential involvement in numerous neurodegenerative diseases associated with diabetes (particularly type 2 diabetes) and aging mediated less than 20 years." (PMID 22500228, 2012). "Women with PCOS have been considered to be insulin resistant, and are at markedly high risk for developing diabetes." (PMID 22309801, 2012). "Vitamin D deficiency has been associated with impaired human insulin action, suggesting a role in the pathogenesis of diabetes mellitus type 2 (T2DM)." (PMID 22809461, 2012). "We then performed an integrative analysis to investigate the inter-relationship among genetic factors, expression traits, and plasma insulin, a hallmark diabetes trait, and developed a novel method for inferring key regulators for regulating plasma insulin." (PMID 23236292, 2012). "Diabetes mellitus, a leading metabolic disorder worldwide, is characterized by hyperglycemia associated with impairment in insulin secretion and/or insulin action as well as alteration in intermediary metabolism of carbohydrate, protein and lipids." (PMID 22734822, 2012). "UCP2, a well-known inner mitochondrial membrane protein, responsible for energy dissipation and heat production, has been found to associate with obesity, diabetes and regulation of insulin secretion." (PMID 22369239, 2012). "The widely-used practice guidelines detailed in the American Diabetes Association and the European Association for the Study of Diabetes consensus statement recommends progression if HbA1c levels remain ≥7% after 3 months of basal insulin therapy." (PMID 22999494, 2012). "The Akita mouse carries a mutation for the Ins2 gene which disrupts a disulfide bond between the α and β chain of proinsulin, leading to the mis-folding of the mutated insulin, and by which the mutated insulin induces ER stress in β cells to cause diabetes." (PMID 22454627, 2012). "The Diabetes Control and Complications Trial reported that tight control of diabetes with insulin reduced the 36-month risk of progression to retinopathy by 76% (95% CI: 62-85%)." (PMID 22646811, 2012). "Several genes were ontologically associated with regulation of insulin signaling and secretion, diabetes, and islet physiology." (PMID 22655170, 2012). "In human Type 2 diabetes and in the mouse model of obesity-associated diabetes, a marked deficiency of β-cell glucose transporters and glucose uptake occurs with the loss of glucose-stimulated insulin secretion." (PMID 23300881, 2012). "Hyperglycemia associated with diabetes mellitus can be controlled by diet management, exercise, oral hypoglycemic agents, and insulin therapy." (PMID 23320026, 2012). "In T1D, far fewer reports have focused on the role of exercise, but more recent studies suggest that exercise improves blood glucose regulation, reduces the daily insulin dosage and decreases the risk of diabetes-associated complications in people with T1D." (PMID 23251813, 2012). "Older age, longer duration of diabetes and treatment with insulin were associated with all markers of vascular dysfunction, although each marker appeared to be independently associated with specific distinct parameters." (PMID 23062182, 2012). "The association between type 2 diabetes/insulin use and HP eradication was evaluated by logistic regression, considering the confounding effect of diabetes duration, comorbidities, medications and panendoscopic examination." (PMID 22571603, 2012).
diabetes (continued). "By preventing hyperglycemia-induced oxidative stress and the associated pancreatic β-cell destruction, Aloe vera plant extracts increase insulin secretion via the pancreas, thus ameliorating diabetes-associated hyperglycemia and dyslipidemia." (PMID 23117427, 2012). "For example, our comparative phenotype analysis identified phenotypes of insulin resistance, increased circulating insulin level and impaired glucose tolerance; traits associated with the feline hereditary disease of diabetes mellitus." (PMID 22257742, 2012). "We performed an integrative analysis to investigate the inter-relationship among genetic factors, expression traits, and plasma insulin, a hallmark diabetes trait." (PMID 23236292, 2012). "For example, we showed that the effect of diabetes risk SNPs on insulin secretion is only apparent in insulin resistant individuals." (PMID 22768041, 2012). "If HCQ improves insulin sensitivity in people with systematic rheumatic disease, a diabetes prevention trial should be considered for high risk patients with RA or SLE." (PMID 22676348, 2012). "CABG patients possessed a significantly higher burden of cardiovascular risk factors (diabetes and dyslipidemia) and medications (antiplatelet drugs, statins, nitrates, oral antidiabetics and insulin)." (PMID 22214418, 2012). "It is likely that these elevations in liver enzymes reflect increasing fatty liver and mechanisms linking excess hepatic fat with insulin resistance are now well established such that fatty liver is an established risk factor for diabetes." (PMID 23112853, 2012). "Polymorphisms in PPARG, particularly the proline-to-alanine substitution at aminoacid position 12, have been associated with diabetes, insulin levels, insulin sensitivity, body mass index, and dyslipidemia." (PMID 22523693, 2012). "It improves the psychological results, the reproductive conditions (menstrual cycle, ovulation, and fertility), and the metabolic conditions, insulin resistance, cardiovascular risk factors and those of diabetes mellitus." (PMID 22778733, 2012). "Diabetes mellitus (DM) is a chronic disease caused by inherited or acquired deficiency in insulin secretion and by decreased responsiveness of the organs to secreted insulin." (PMID 22924034, 2012). "Unbiased bioinformatics analyses (KEGG and LSI), revealed that many pathways and proteins associated with diabetes and insulin signaling were significantly altered in the tgHD rats." (PMID 23094041, 2012). "Patients with diabetes often considered starting insulin therapy as a complex task and this caused patients to delay insulin therapy." (PMID 22469132, 2012). "The arachidonic acid-derived OxLs (i.e. eicosanoids) are known to influence insulin signaling, inflammation and vascular function with mechanistic implications at the tissue level in diabetes and associated pathologies." (PMID 23144998, 2012). "Vitamin D deficiency has been associated with a multitude of disorders including diabetes, defective insulin secretion as well as rickets and poor bone health." (PMID 22681928, 2012). "Diabetes was defined as a fasting plasma glucose of ≥126 mg/dL or HbA1c of ≥6.5% according to the American Diabetes Association criteria, or treatment with oral hypoglycemic drugs or insulin." (PMID 22685652, 2012). "Our findings showed that increased glycemic levels or BMI, and decreased insulin sensitivity, were particularly relevant for the risk of developing diabetes." (PMID 23185618, 2012). "Diabetes is a disease characterized by chronic hyperglycemia secondary to a reduction in the functional efficacy and/or a deficiency of insulin." (PMID 22257425, 2012). "In conclusion, the results presented here demonstrate that STZ-induced insulin-deficient diabetes exacerbates Aβ accumulation by elevating expression levels of the β-secretase enzyme BACE1 and its substrate APP in the 5XFAD mouse model of AD." (PMID 22403710, 2012).
diabetes (continued). "Age, diabetes duration, daily insulin dose, microalbuminuria, and major cardiovascular risk factors including anthropometric and metabolic parameters were assessed in each patient." (PMID 22394699, 2012). "Many of the metabolic conditions associated with diabetes, including hyperglycemia, excess free fatty acid liberation, and insulin resistance mediate abnormalities in endothelial cell function by affecting the synthesis or degradation of NO." (PMID 22611498, 2012). "Type 1 diabetes mellitus (T1DM) is caused by the selective destruction of insulin-producing β-cells." (PMID 22393382, 2012). "Total WBC count is also associated with insulin sensitivity such that an increase in total WBC count is indicative of an increased risk of future type 2 diabetes mellitus." (PMID 22363616, 2012). "Pancreatic β-cell failure in diabetes is characterized primarily by progressive loss of insulin production and β-cell mass." (PMID 22470529, 2012). "Accordingly, PIHO disorder would contribute to β-cell defects in diabetes of general forms in addition to monogenic diabetes with heterogeneous mutations in the insulin gene." (PMID 22509386, 2012). "An expert consensus group with representatives from The American Diabetes Association and the European Association for the Study of Diabetes recommended that people with T2DM begin insulin with a basal insulin regimen." (PMID 22519930, 2012). "It is particularly important that some diabetes patients have increased risk of hypoglycemia during insulin treatment therapy." (PMID 22969729, 2012). "Cross-sectional and prospective studies have shown that voluntary sleep curtailment to 6 hours or less per day is associated with increased fasting glucose levels, hyperinsulinaemia and reduced insulin sensitivity, leading to an increased risk of diabetes." (PMID 22485135, 2012). "Diseases associated with excessive secretion of insulin antagonistic hormones can cause diabetes (which is typically resolved once the hormone excess is removed)." (PMID 22257465, 2012). "Maintaining fitness can reduce some of the risk factors for heart disease but has less effect on risk factors for diabetes (insulin levels)." (PMID 22693553, 2012). "In conclusion, in fGDM, marked deterioration of insulin sensitivity is associated with diabetes onset." (PMID 23185618, 2012). "Of note, high fasting C-peptide levels were associated with an increased risk of diabetes, and this was confirmed by similar findings on fasting insulin levels and fasting insulin secretion, though with somehow higher P values (P = 0.014 for both)." (PMID 23185618, 2012). "The findings suggest that vitamin D deficiency, possibly involving altered insulin sensitivity, is associated with an increased risk for diabetes mellitus in the Korean population." (PMID 22247968, 2012). "Genetic studies revealed that the ablation of insulin/IGF-1 signaling in the pancreas causes diabetes." (PMID 22384192, 2012). "Vanadium salts have been used to lower glucose levels in diabetes patients even before the discovery of insulin; however the molecular mechanisms underlying the observed effects are not clear." (PMID 22988520, 2012). "Diabetes mellitus (DM) is a chronic metabolic disorder characterized by a deficiency in insulin secretion or an increased insulin resistance, resulting in hyperglycemia." (PMID 22776352, 2012). "Recent studies have shown that the preservation of glucose transport in β-cells maintains normal insulin secretion and blocks the development of obesity-associated diabetes." (PMID 23300881, 2012). "Post-pancreatectomy diabetes is typically brittle, as a result of concomitant deficiency in insulin secretion and counter regulatory hormones, and difficult to manage." (PMID 22385578, 2012). "Monitoring of patient's insulin production ability on the olfactory bulb-derived adult neural stem cells would be also useful in both diabetes treatments and neurological diseases caused by low-insulin levels." (PMID 22988465, 2012).